MICAL2 (microtubule associated monooxygenase, calponin and LIM domain containing 2)
Diseases named in the same sentence as MICAL2 in open-access papers (continued):
Sharing a sentence is not in itself a finding about the gene and the disease.
pancreatic cancer (4 papers, 2011 to 2025). "In pancreatic cancer, GO enrichment analysis indicated that MICAL2 is mostly associated with EMT, ECM architecture, and other biological activities pertinent to tumor metastasis." (PMID 40943497, 2025). "ROC curves revealed that area under the curves of GSE16515 and GSE183795 were 0.826 [95% confidence interval (CI) 0.698–0.929] and 0.857 (95% CI 0.807–0.9), indicating that MICAL2 shows potential as a diagnostic biomarker for pancreatic cancer." (PMID 38326344, 2024). "The results showed that MICAL2 was highly expressed in pancreatic cancer tissue and exhibited potential diagnostic capability." (PMID 38326344, 2024). "Survival analyses have revealed that high MICAL2 expression levels were significantly associated with poor survival rates in patients with pancreatic cancer." (PMID 38326344, 2024). "In this study, we explored the expression level of MICAL2 in pancreatic cancer and normal tissues and evaluated the diagnostic and prognostic capability of MICAL2." (PMID 38326344, 2024). "Furthermore, high MICAL2 expression causes an increase in the stromal components in pancreatic cancer samples." (PMID 38326344, 2024). "However, a higher stromal score was found in the group with high MICAL2 expression (p < 0.05), indicating that MICAL2 was closely associated with the stromal components in pancreatic cancer." (PMID 38326344, 2024). "Furthermore, the ROC curve indicated that MICAL2 shows potential diagnostic capability for pancreatic cancer." (PMID 38326344, 2024). "Furthermore, higher MICAL2 expression in pancreatic cancer was also associated with an increase in cancer-associated fibroblasts as well as M2 macrophage infiltration, and a reduction in CD8 + T cell infiltration, thereby facilitating the formation of an immunosuppressive microenvironment." (PMID 38326344, 2024). "Future research should be directed at gaining a better understanding of the complex mechanism underlying the role played by MICAL2 in promoting the interaction between CAFs and immune cells, as this may enable effective targeted therapy and immunotherapy to be developed against pancreatic cancer." (PMID 38326344, 2024). "To elucidate the cell distribution of MICAL2 expression in pancreatic cancer tissue, we analyzed the single-cell sequencing profile." (PMID 38326344, 2024). "To elucidate the biological function of MICAL2 in pancreatic cancer, we performed GO and KEGG pathway enrichment analyses." (PMID 38326344, 2024). "MICAL2, mainly expressed in fibroblasts of pancreatic cancer, was closely related to metastasis and immune-related features, such as epithelial-mesenchymal transformation, extracellular cell matrix degradation, and inflammatory response." (PMID 38326344, 2024). "To explore the role of MICAL2 in the immune microenvironment of pancreatic cancer, we used the “CIBERSORT” algorithm to calculate the infiltration of 22 immune cells and found that there were notable differences between the CD8 + T cells and M2 macrophages." (PMID 38326344, 2024). "The results showed that high MICAL2 expression in pancreatic cancer represented low tumor purity (p < 0.05), which indicates higher tumor heterogeneity." (PMID 38326344, 2024). "In pancreatic cancer, GO enrichment analysis revealed that MICAL2 is mainly enriched in EMT, ECM organization, and other biological functions related to tumor metastasis." (PMID 38326344, 2024). "To further determine the specific function of MICAL2 in pancreatic cancer, we calculated the stromal score and tumor purity using the TCGA dataset." (PMID 38326344, 2024). "Our results helped elucidate the clinical value and function in metastasis and immunity of MICAL2 in pancreatic cancer." (PMID 38326344, 2024). "The ability of MICAL2 to regulate the SRF/MRTF-A target genes was also seen when we examined a pancreatic cancer gene expression analysis." (PMID 38137053, 2023). "In our study, we found that MICAL2 was highly expressed in pancreatic cancer samples." (PMID 38326344, 2024).
pancreatic cancer (continued). "In conclusion, our study revealed that MICAL2, mainly expressed in fibroblasts, is an independent and adverse prognostic factor and facilitates metastasis and the formation of immunosuppressive microenvironment in pancreatic cancer." (PMID 38326344, 2024). "We used public datasets on pancreatic cancer to analyze the differential expression of MICAL2." (PMID 38326344, 2024). "It was further illustrated that MICAL2 may act as a prognostic biomarker for pancreatic cancer." (PMID 38326344, 2024). "However, the biological function of tumorigenesis and the prognostic impact of MICAL2 in pancreatic cancer remains unclear." (PMID 38326344, 2024). "However, the role played by MICAL2 in pancreatic cancer remains unclear." (PMID 38326344, 2024). "A strong correlation was observed between MICAL2 and M2 macrophages biomarker CD163 in the TCGA dataset (r = 0.512, p < 0.05), while immunohistochemistry staining showed that more CD163-positive cells were observed in the MICAL2high patient with pancreatic cancer compared with the MICAL2low patient." (PMID 38326344, 2024).
glioblastoma (3 papers, 2021 to 2024). The most malignant astrocytic tumor (WHO grade IV). "High expression of MICAL2 is associated with poor prognosis for glioblastoma patients, as well as the promotion of glioblastoma in mice." (PMID 38326344, 2024). "High MICAL2 expression was recognized as a risk factor for overall survival (p = 0.011 < 0.05) in patients with primary glioblastoma by log-rank test." (PMID 34868922, 2021). "The high MICAL2 expression level was identified as a risk factor for overall survival in patients with primary glioblastoma." (PMID 34868922, 2021). "High MICAL2 expression could be identified as a risk factor for overall survival in patients with primary glioblastoma." (PMID 34868922, 2021). "Reportedly, MICAL2 expression in the neoangiogenic endothelium of gastric, renal, breast, glioblastoma, and cardiac mucinous tumors was closely correlated with angiogenic activity resulting from the inflammatory response." (PMID 38326344, 2024). "In the future, understanding the molecular pathways involved in MICAL2 will help develop new targeted therapies for glioblastoma and improve currently available therapies." (PMID 34868922, 2021). "To further analyze the relationship between TGF-β and E-cadherin, N-cadherin, and vimentin, the marker proteins of EMT, we selected 16 cases of glioblastoma with the highest and lowest expression levels of MICAL2 in the TCGA database, respectively." (PMID 34868922, 2021). "MICAL2-knockdown inhibited the proliferation of glioblastoma cells, which was related to cell cycle arrest and downregulation of DNA replication." (PMID 34868922, 2021). "We then evaluated the impact of MICAL2 expression on the prognosis of patients with primary glioblastoma using data obtained from the GEPIA." (PMID 34868922, 2021). "Further experiments revealed that MICAL2 could promote the growth of glioblastoma cells both in vitro and in vivo." (PMID 34868922, 2021). "However, the role of MICAL2 on glioblastoma progression and the mechanisms behind it are still unknown." (PMID 34868922, 2021). "Here, we found that MICAL2 interacts with TGF receptor-type I (TGFRI) and promotes the proliferation and migration of glioblastoma through the TGF-β/p-Smad2/EMT-like signaling pathway." (PMID 34868922, 2021). "In our study, MICAL2 was widely expressed and coexpressed with TGF receptor-type I (TGFRI) in glioblastoma and was positively correlated with the expression of p-Smad2, which lies downstream of TGF-β." (PMID 34868922, 2021). "Moreover, MICAL2 interacts with TGFRI and promotes the proliferation of glioblastoma cells through the EMT pathway." (PMID 34868922, 2021).
kidney cancer (3 papers, 2016 to 2020). Primary or metastatic malignant neoplasm involving the kidney. "MICAL2 knockdown caused a reduction in viability and loss of motility and invasion in 786-O kidney cancer cells, suggesting that MICAL2 might be a promising target for anti-metastatic therapy." (PMID 32478077, 2020). "We found MICAL2 significantly over-expressed in poorly differentiated and undifferentiated gastric and kidney cancer, compared with more differentiated carcinomas." (PMID 26689989, 2016). "To identify the cellular distribution of MICAL2 expression, we performed immunohistochemistry (IHC) analyses of histological sections of gastric and kidney cancer, using specific anti-MICAL2 polyclonal antibodies generated in our laboratory." (PMID 26689989, 2016). "So, MICAL2 expression inversely correlated with proliferation also in kidney cancer." (PMID 26689989, 2016).
metastatic disease (2 papers, 2016 to 2021). "Altogether our data indicate that MICAL2 over-expression is associated with cancer progression and metastatic disease." (PMID 26689989, 2016). "MICAL2 expression is at a high level in the primary and metastatic tumor, as indicated in the EMT state." (PMID 34868922, 2021). "In conclusion, this is the first work to show data from human cancer and in vitro analyses suggesting that MICAL2 represents a marker of metastatic disease that promotes migration and invasion of epithelial cancers." (PMID 26689989, 2016).
pulmonary arterial hypertension (2 papers, 2020 to 2023). Pulmonary arterial hypertension (PAH) is a group of diseases characterized by mean pulmonary artery pressure >20 mmHg and elevated pulmonary arterial resistance leading to right heart failure. "MiR-205-5p expression was reduced in pulmonary arterial hypertension and miR-205-5p suppressed the proliferation of pulmonary vascular smooth muscle by binding MICAL2 mRNA." (PMID 32495824, 2020).
aging (1 paper, 2022). A developmental process that is a deterioration and loss of function over time. "Our findings suggested that Mical2 was implicated in skin aging." (PMID 36271377, 2022).
atherosclerosis (1 paper, 2022). A disease characterized by the build-up of fatty material and calcium deposition in the arterial wall resulting in partial or complete occlusion of the arterial lumen. "Published GWAS have shown common variants in MICAL2 to be significantly associated with resting heart rate and white blood cell count, traits which can influence atherosclerosis and vascular events." (PMID 35020748, 2022). "Together, these findings in conjunction with our current study, offer biologic plausibility for AMPD3 and MICAL2 in atherosclerosis." (PMID 35020748, 2022). "Our study suggests that rare variation in genes including AMPD3, MICAL2, DPP6, and DENND2B may play a role in subclinical atherosclerosis, thereby making them promising novel candidates for the development of anti-atherosclerotic therapies." (PMID 35020748, 2022).
bladder tumors (1 paper, 2021). "MICAL2 is overexpressed in bladder tumors and participates in its pathogenesis." (PMID 34868922, 2021).
brain tumor (1 paper, 2021). "The impacts of MICAL2 on tumor growth in an orthotopic brain tumor model were observed by MRI, bioluminescence, HE staining, and Western blotting." (PMID 34868922, 2021). "Besides, the tumor volume in the scramble control group was larger compared with that of the MICAL2 knockdown group in both the orthotopic brain tumor model and the subcutaneous tumor model, suggesting that MICAL2 promotes the proliferation of glioma cells in vivo." (PMID 34868922, 2021).
diffuse gastric adenocarcinoma (1 paper, 2022). An adenocarcinoma arising from the stomach. "Data from Oncomine showed that MICAL2 expression was significantly higher in diffuse gastric adenocarcinoma, gastric intestinal-type adenocarcinoma, and gastric mixed adenocarcinoma than in normal gastric mucosa." (PMID 36064550, 2022).
glioma (1 paper, 2021). A benign or malignant brain and spinal cord tumor that arises from glial cells (astrocytes, oligodendrocytes, ependymal cells). "At first, we found that the expression levels of TGF-β and MICAL2 were higher in high-grade glioma cells and that MICAL2 was associated with higher p-Smad2 upon evaluation, using immunohistochemistry." (PMID 34868922, 2021). "In a word, the experimental results implied that MICAL2 promotes the proliferation of glioma cells in vivo." (PMID 34868922, 2021). "Understanding the molecular mechanism of MICAL2 participating in the invasion and metastasis of glioma cells can help us elucidate the molecular basis of the disease." (PMID 34868922, 2021). "In this present study, MICAL2 promotes proliferation and migration of glioma cells through the TGF-β/EMT signaling pathway." (PMID 34868922, 2021). "The immunohistochemical result showed that the expression of TGF-β, MICAL2, and p-Smad2 was increased with the grade of glioma." (PMID 34868922, 2021). "The expression of TGF-β, MICAL2, and p-Smad2 in different-grade gliomas was analyzed using immunohistochemistry." (PMID 34868922, 2021). "Mechanistically, MICAL2 promotes the proliferation and migration of glioma cells through the TGFRI/EMT signaling pathway." (PMID 34868922, 2021). "PCNA was served as a DNA clamp for DNA polymerase to participating in DNA replication; cyclin D primarily controls the transition in mammalian cells from phase G1 to phase S, indicating that the knockdown of MICAL2 inhibited the proliferation of glioma cells." (PMID 34868922, 2021). "The results demonstrated increased migration capability as compared with the scrambled control cells (p < 0.05) in U87 cell lines, and we observed the same result (p < 0.05) in U251 cell lines, suggesting that downregulation of MICAL2 can promote the invasive ability of glioma cells." (PMID 34868922, 2021). "We also evaluated their effects on the EMT-like process of glioma cells and found downregulation of MICAL2 and TGFRI could inhibit the EMT-like process of glioma cells." (PMID 34868922, 2021). "To confirm whether MICLA2 promotes the proliferation of glioma in nude mice, we injected MICAL2 knockdown cells subcutaneously into the dorsal side of the mice." (PMID 34868922, 2021). "The results also indicated that MICAL2 binded with TGFRI and promoted EMT-like process of glioma cells through TGFRI/p-Smad2 signaling pathway." (PMID 34868922, 2021). "Then, we constructed MICAL2 knockdown shRNA and TGFRI knockdown shRNA and evaluated their effects on the ability of glioma cells to invade and migrate in U87 and U251 cell lines." (PMID 34868922, 2021). "We used the TGF-β-induced glioma to simulate the EMT-like model and MICAL2 were knocked down using shMICAL2." (PMID 34868922, 2021). "The results confirmed that the downregulation of MICAL2 in GBM would inhibit proliferation and migration of glioma cells and have explained the signaling pathway behind it." (PMID 34868922, 2021).
lung adenocarcinoma (1 paper, 2022). A carcinoma that arises from the lung and is characterized by the presence of malignant glandular epithelial cells. "High cytoplasmic MICAL2 and/or total MICAL2 expression levels were also identified as positively correlated with lymphatic metastasis and shorter OS of lung adenocarcinoma patients." (PMID 36575439, 2022).
lung carcinoma (1 paper, 2022). "Additionally, high MICAL2 expression has been associated with lymphatic metastasis and shorter OS in lung cancer patients." (PMID 35501725, 2022).
muscle disorders (1 paper, 2020). "Thus, MICAL2 is a novel regulator of skeletal myogenic differentiation and a possible therapeutic target for muscle disorders." (PMID 32811811, 2020).
psoriasis (1 paper, 2024). An autoimmune condition characterized by red, well-delineated plaques with silvery scales that are usually on the extensor surfaces and scalp. "Flow cytometry analysis also showed that γδ T cells from IMQ-induced psoriasis mice had higher levels of MICAL1 and MICAL2 expression." (PMID 38566145, 2024).
rhabdomyosarcoma (1 paper, 2020). A rare aggressive malignant mesenchymal neoplasm arising from skeletal muscle. "For this reason, we are currently investigating the role of MICAL2 in different rhabdomyosarcoma cell lines." (PMID 32811811, 2020).
thyroid cancer (1 paper, 2024). "To uncover the most distinct genes in different thyroid cancer subtypes, we screened BCL2, BHLHE40, MICAL2, TGM2, and TPO by comparing each pair of existing subtypes." (PMID 39872516, 2024).